MMP3 (matrix metallopeptidase 3)
Diseases named in the same sentence as MMP3 in open-access papers (continued):
Sharing a sentence is not in itself a finding about the gene and the disease.
tumor (continued). "We further hypothesized that MMP3 influences the neoplastic process not only at the stage of early tumorigenesis as originally reported, but also at later stages of tumor progression to metastatic disease." (PMID 26008967, 2015). "The mRNA expression of some proliferation and invasion related genes such as CCND3, CCNE1, Ki-67 and MMP3 were all down-regulated in miR-15a/miR-16-1 overexpression group, elucidating the tumor-suppressive functions of miR-15a and miR-16-1 in gastric tumorigenesis." (PMID 25743273, 2015). "One unexpected finding of our study is the localization of MMP3 primarily to tumor cells; this is somewhat surprising since MMPs have been generally believed to derive mainly from the tumor stroma, where they have been found to play important roles in shaping the tumor microenvironment." (PMID 26807201, 2015). "In summary, we found that modulation of MMP3 expression/function could significantly alter malignant behavior of established tumor cell line models in part in a cell-intrinsic manner." (PMID 26008967, 2015). "The reduction in MMP-3 expression may itself contribute to the enhanced tumor and metastatic capability of MMTV-PyMT tumors in the Mmp8-null background." (PMID 25848906, 2015). "Thus, both MMP3 protein and its downstream mediator Rac1b are highly expressed in cancer cells in these three tumor types." (PMID 26807201, 2015). "Importantly, using the orthotopic 4T1 model of spontaneous metastasis, we demonstrated that diminution of tumor-derived MMP3 expression significantly prolonged survival in a post-surgical setting." (PMID 26008967, 2015). "Conversely, molecular approaches to silence MMP3 expression in more highly aggressive tumor populations which expressed higher basal levels of MMP3 (CMS4.met.sel or 4T1) led to significant declines in primary tumor growth, as well as experimental or spontaneous metastasis." (PMID 26008967, 2015). "Here, we focused on whether alterations in MMP3 expression could affect tumor cells in a cell-intrinsic manner." (PMID 26008967, 2015). "Our identification of an oncogenic MMP3-Rac1b signaling axis as a driver of tumor growth and progression of multiple common poor prognosis cancers suggests that new therapies to target this pathway may hold substantial clinical promise." (PMID 26807201, 2015). "Indeed, we observed a direct correlation between endogenous MMP3 levels and invasive phenotype in all tumor models tested, as measured by in vitro invasion assays." (PMID 26008967, 2015). "MMP-3 (stromelysin-1), specifically, has been shown to cause EMT and to induce a premalignant phenotype in cultured mammary epithelial cells, and to stimulate spontaneous tumor formation when expressed in mouse mammary glands." (PMID 24811539, 2014). "Furthermore, inhibition of integrin ανβ6 markedly downregulated the expression of matrix metalloproteinase-9 (MMP-9), matrix metalloproteinase-3 (MMP-3) and urokinase plasminogen activator (uPA) in tumor conditioned medium." (PMID 25176506, 2014). "It is noted that relatively high levels of MMP9 and MMP3 in the patient tumor sample were detected." (PMID 22873525, 2012). "Using immunocytochemistry, we could confirm our data obtained by RT-PCR and Western Blot analysis in this cell line, as we found a weak staining for MMP-3 in the cytoplasm and nuclei of the tumor cells." (PMID 19531263, 2009). "Furthermore, only a weak staining of MMP-3 was found in tumor cells using immunohistochemistry, which thus correlates with published results." (PMID 19531263, 2009).
tumor (continued). "When IPC was related to genotype, higher levels of IPC were generated by tumor fibroblasts with the high-expressing MMP-3 5A/5A genotype compared with the 5A/6A and 6A/6A genotypes (p = 0.05 and 0.07, respectively), and this was associated with enhanced MMP-3 release." (PMID 17922906, 2007). "This revealed a consistent and highly significant reduction in tumor cell invasion in the presence of the MMP-3 inhibitor compared with vehicle-only control assays (p = 0.005), thus supporting a role for fibroblast-derived MMP-3 activity in promoting tumor cell invasion." (PMID 17922906, 2007). "It is plausible that epigenetic alterations, such as demethylation (which is common in tumors), may unmask the high-expressing potential of the MMP-3 5A/5A genotype in tumor fibroblasts." (PMID 17922906, 2007). "Furthermore, the MMP-3 5A/5A genotype and high IPC were reflected in higher levels of MMP-3 activity in tumor-derived fibroblasts, although the normal donor fibroblasts of MMP-3 5A/5A genotype did not exhibit enhanced MMP-3 activity." (PMID 17922906, 2007). "Both MMP-1 and MMP-3 have been shown to affect the motility and invasion of tumor cells directly." (PMID 17922906, 2007). "However, this does not appear to have influenced the detection of the MMPs as indicated by the moderate levels of all MMPs examined in both compartments in the MCF-7 xenograft, and the moderate level of MMP-3 in the Hs578T tumour compartment." (PMID 16430785, 2006). "MMP-3 mRNA was localised to the tumour component in all six xenograft samples examined." (PMID 16430785, 2006). "In addition to extracellular matrix degradation, MMP3 activates gelatinase B and collagenases and releases cell surface molecules including E-cadherin, which in turn promote tumour growth." (PMID 12402142, 2002). "Furthermore, we assessed the effectiveness of MMP3-siRNA in the tumor tissues of mice." (PMID 40362252, 2025). "Importantly, higher MMP-3 expression was observed with increasing tumor stage (according to FIGO)." (PMID 38892452, 2024). "Furthermore, the upregulation of MMP-2, MMP-3, and myeloperoxidase highlights the role of these tumors in host-immune interactions, while the decrease in osteopontin and proliferin suggests a shift toward a less favorable tumor microenvironment." (PMID 38890285, 2024). "However, there is evidence that if there is excessive TIMP1 in the tissue, it may activate other MMPs, such as MMP-3, or promote tumor invasion and metastasis through other modes of action." (PMID 36158681, 2022). "Therefore, IL-1β-mediated-MMP-3 may contribute to malignant tumor processes by creating a suitable microenvironment for tumor development and progression." (PMID 36445856, 2022). "Therefore, MMP3 has been suggested as a natural tumor-promoting factor." (PMID 35269560, 2022). "While we found the higher expression of MMP3 in TC vs. AC, despite the lower aggressiveness of the former tumor type, the higher expression of SNAI2 may justify some TC cases with favorable pathologic features following an unpredictable unfavorable clinical course." (PMID 36553576, 2022). "Although the PDS model had different specific analytes for the two most strongly correlated with a shorter PFI, we noted that it also had highly ranked proteases (MMP-3 and uPA urokinase), providing additional support that tumor remodeling during treatment may provide clues to recurrence." (PMID 36077825, 2022). "Thus, the increase in MMP1 and MMP3 expression observed after the knockdown of the ELOVL5 and IGFBP6 genes is consistent with the hypothesis that ELOVL5 and IGFBP6 are associated with tumor metastatic potential." (PMID 34149804, 2021). "However, there remains a lack of knowledge of CCN2/CTGF role/functions in cancer progression in vivo in the MMP3 switching on CCN2/CTGF gene as well as the role of the C-terminus of CCN2/CTGF cleaved by MMP3 and their spatial distribution during activation and tumor progression." (PMID 32260433, 2020).
tumor (continued). "Besides, we have shown that not only MMP3 but also MMP9 were crucial in LuM1 tumor progression." (PMID 32260433, 2020). "Interestingly, MMP3 have been demonstrated to over-express in various human tumor tissues." (PMID 32922541, 2020). "Our study indicates that the rapidly metastatic tumor-derived, MMP3-rich EVs were rapidly transmissive, invasive to tissues and cells, and powerfully pro-tumorigenic, suggesting that MMP-rich EVs could be conceptual oncosomes involving primary and secondary tumorigenesis." (PMID 32260433, 2020). "In addition, MMP-3 enhances the migratory and invasive abilities of tumor cells." (PMID 31601869, 2019). "Indeed, a recent investigation revealed that SPOCK1-promoted tumor growth and metastasis are accompanied by upregulation of MMP-3 and MMP-9 expressions in PCa, suggesting that MMPs may be involved in the SPOCK1-mediated EMT process and subsequent metastasis." (PMID 31182131, 2019). "In addition, 3T3-A-EXO increased MMP3 protein level in 3LL tumor cells." (PMID 29137230, 2017). "In addition, MMP3 protein levels are positively correlated with MMP9 activity in tumor tissues." (PMID 29137230, 2017). "In addition, 3T3-A-EXO is enriched in MMP3 mRNA and protein, which could be transferred into 3LL tumor cells." (PMID 29137230, 2017). "Thus, MMP-1 and MMP-3 transcripts were apparently decreased after treatment with sorafenib, providing a possible explanation for its potent roles on controlling KF migration as well as tumor cell invasion and metastasis." (PMID 27339758, 2016). "MMP3 might be a potential anticancer target to block the tumor-stroma interplay." (PMID 26992208, 2016). "Additionally, MMP-3 fragments were observed in the nucleus of several tumor cell lines." (PMID 27764205, 2016). "Additionally, we observed that MMP3 polymorphisms were associated with tumor grade, with women having a much higher risk of a non-differentiated tumor if they had the rare variant of the MMP3 polymorphisms." (PMID 23696797, 2013). "However, recent studies indicate that MMP-3, as well as other MMPs, may also have tumour-suppressive effects." (PMID 22500976, 2012). "The expression of MMP-3 in carcinogenesis is regulated primarily at the transcriptional level, but there is also evidence of modulation of mRNA stability in response to growth factors and cytokines secreted by tumour-infiltrating inflammatory cells as well as by tumour and stromal cells." (PMID 20630073, 2010). "However, high MMP-3 and -9 proteolytic enzyme levels also may support tumor cell proliferation, angiogenesis, invasion and metastasis by degrading type IV collagen, penetrating the basement membrane and invading surrounding tissues." (PMID 18636124, 2008). "MMP3, also known as stromelysin-1, is an ECM remodeling enzyme involved in metastasis and tumor progression." (PMID 41583390, 2026). "Mechanistically, our data reveal that knockdown of KRAS inhibits matrix metalloproteinase (MMP1), MMP3, and MMP9, which are known as tumor metastasis-related proteins, via an IL-17 signal-dependent manner." (PMID 40486048, 2025). "Data generated from our studies clearly demonstrated that Spry1KO led to the down-regulation of several MMPs, including MMP-2, MMP-3 and MMP-8, which have been recently explored as targets to hamper cancer angiogenesis and, in turn, tumor cell dissemination." (PMID 39953610, 2025). "TGF-β facilitates EMT, enabling tumor cells to detach, invade, and survive in the circulation, while SASP-driven MMP1, MMP3, and other matrix metalloproteinases degrade the ECM (extracellular matrix), creating physical pathways for tumor dissemination." (PMID 41373662, 2025). "MMP3 can degrade the basement membrane and ECM, subsequently reducing adhesion in cells and providing conditions conducive to the migration of tumor cells, which serves as a crucial facilitator of metastasis in ESCC25,48." (PMID 39741182, 2025).
tumor (continued). "Increased COL11A1 expression, through the regulation of TGF-β3, activates CAFs via the NF-κB/IGFBP2 axis and also affects tumor aggressiveness and therapy resistance through the TGF-β1/MMP3 axis." (PMID 40136652, 2025). "Prior research has shown that MMP2, MMP3, and MMP9 can modulate the breakdown of nearly all extracellular matrix constituents, hence enhancing tumour motility, invasion, and metastasis." (PMID 39858466, 2025). "Downstream analysis of genes involved in the migration of tumor cell lines revealed that MSI2 was the top regulator of migration, with a log ratio of 4.514, followed by MMP3, MMP1, and IL1β." (PMID 39990676, 2025). "In this work, we present a continuation of the evaluation of matrilysins (MMP-7 and MMP-26) and stromelysins (MMP-3 and MMP-10) as novel tumor markers for women’s diseases —this time, as screening biomarkers of EC." (PMID 40332487, 2025). "Among these, matrix metalloproteinase (MMP) family members—including MMP1, MMP3, MMP9, and MMP11—exhibited significant upregulation, consistent with their established roles in promoting tumor invasiveness." (PMID 40361356, 2025). "Collectively, these findings indicate that araliadiol attenuates AP-1 activation and suppresses MMP-1 and MMP-3 expression in senescent dermal fibroblasts, thereby potentially protecting against ECM degradation and skin aging." (PMID 41471076, 2025). "In short, we identified an exclusive tumor cell subpopulation MP3 in D‐TGCT and confirmed the role of these tumor cells in regulating differentiation of CD34+ Fbs toward APOE+ Fbs and MMP3+ Fbs through COL6A3 − (ITGAV + ITGB8) interaction." (PMID 40126353, 2025). "Treatment with the chimera also suppressed tumor angiogenesis, evidenced by reduced expression of key angiogenic mediators, including VEGF, MMP-3, and ANG-1." (PMID 41402667, 2025). "MMP3 (matrix metalloproteinase 3) supports EMT by degrading extracellular matrix components, enabling greater tumor cell invasion and metastasis." (PMID 41266827, 2025). "We thereby established a correlative CCI network and identified strong interactions between tumor cells and Fbs that were CD34+, MMP3+, or APOE+." (PMID 40126353, 2025). "Analysis of the DEGs in TCGA tumours revealed that the miR-18a/low tumours expressed high levels of EMT master regulators-ZEB1 and ZEB2 and Matrix metalloproteinases, MMP2, MMP3, MMP10, MMP11, MMP13 and MMP17 (p < 0.05)." (PMID 38786043, 2024). "MMP3 is a member of the MMP family, which is believed to play an important role in tumor invasion and metastasis." (PMID 39157383, 2024). "Our analysis using the HNSCC dataset of TCGA database revealed significantly elevated expression of MMP1, MMP3, MMP12, and SPP1 in tumor tissues compared to normal tissues." (PMID 39596132, 2024). "MMP3 activation, in turn, triggered MMP9 in 3LL cells, emphasizing the crucial role of MMP3, packaged into exosomes, in promoting tumor invasion." (PMID 39308520, 2024). "The remaining genes were downregulated in all tumor groups, with the most pronounced changes observed for MMP8, MMP3, and MMP10." (PMID 38474106, 2024). "Prognosis analysis further supported the involvement of ECM1, MMP3, and S100A2 in the development of BC, as indicated by their elevated levels in human tumor biopsies." (PMID 38402239, 2024). "This includes the decline in immune function due to the aging of immune cells, as well as the senescence-associated secretory phenotype (SASP) resulting from fibroblast senescence, which contains factors such as MMP3 and VEGF that can promote tumor growth." (PMID 38887516, 2024). "As expected, MMP1, MMP3, MMP12, and SPP1 displayed significantly higher expression in tumor tissues compared to normal samples." (PMID 39596132, 2024). "Here, we observed that CAFs grown in 3D cultures upregulated a variety of MMPs such as MMP-1, MMP2, MMP3, and MMP9, which are major players in tumor angiogenesis, tissue remodeling, repair, and maintenance." (PMID 39700125, 2024).
tumor (continued). "For instance, during tumor initiation, studies have indicated a role for MMP-3 (stromelysin-1), an enzyme capable of degrading various ECM components, including collagen (types II, III, IV, IX, and X), proteoglycans, fibronectin, laminin, and elastin." (PMID 37760801, 2023). "Perioperative continuous intravenous infusion of Lido and Dex significantly reduced the production of NETs (MPO and H3Cit) and the expression of tumor metastasis biomarkers (VEGF-α, MMP-3, and MMP-9) in the peripheral blood of NSCLC patients." (PMID 36910600, 2023). "MMP2 and MMP3 can degrade multiple components of basement membrane and extracellular matrix, and MMP9 is able to induce tumor cells to infiltrate and metastasize into adjacent normal tissues through the injured basement membrane." (PMID 37100464, 2023). "This study will evaluate tumor metastasis biomarkers (VEGF-A, MMP-3, MMP-9), inflammatory factors, immune function and clinical outcomes." (PMID 36910600, 2023). "The PPI network indicated that SSA1 was co-expressed with MMP1, MMP3, and MMP9; together, they played an important role in tumor invasion and metastasis." (PMID 37081987, 2023). "While exploring the effects of tumor metastasis biomarkers, inflammatory factors, and cellular immunity on NETs, we found that VEGF-α, MMP-3, and MMP-9 were positively correlated with NETs, which is mechanistically plausible based on previous studies." (PMID 36910600, 2023). "Studies have indicated that SPOCK1 can promote the abnormal activation of MMP-3, MMP-9, and MMP-2, leading to directed migration of tumor cells from the edge of the tumor mass and ultimately inducing ECM remodeling." (PMID 38087364, 2023). "In our study, we found several MMP molecules to be significantly overexpressed in metastatic cell lines compared to primary tumor cells (e.g., MMP1, MMP2, MMP3, MMP9), with a dramatic increase registered for MMP2." (PMID 37047539, 2023). "Among the various markers identified in the tumor tissues, a proliferation-inducing ligand (APRIL/TNFSF13), B cell activating factor (BAFF), and matrix metalloproteinase-3 (MMP-3) showed significantly high concentrations." (PMID 37511338, 2023). "Overexpression of MMP3, detected in adenomas and early-stage CRC, is suggestive of its involvement in tumor initiation." (PMID 37760801, 2023). "MMPs exert important effects in tumor invasion and metastasis, among which MMP2, MMP3 and MMP9 are the main members that play crucial roles in the invasion and metastasis of cancer cells." (PMID 37100464, 2023). "Rebimastat, an inhibitor of MMP-1, MMP-2, MMP-3, MMP-8, MMP-9, MMP-13, and MMP-14, significantly abolishes tumor growth and abrogates BC metastasis." (PMID 36993955, 2023). "Functional inactivation of FBXW7 led to activation of the MAPK signaling pathway and upregulation of the downstream MMP3 and VEGFA, which enhanced tumor proliferation cell invasion and migration." (PMID 36991467, 2023). "Significant correlations were also found between MMP-3 and TIMP-4 levels, and some variables related to patient characteristics and tumour biology, such as menopausal status tumour classification, differentiation grade and E-cadherin presence." (PMID 38203696, 2023). "Matrix metalloproteinases MMP1, MMP2, MMP3 and MMP9, which are involved in extracellular matrix (ECM) remodeling and promotion of tumor cell migration and invasion, were also significantly increased (p < 0.0001) in metastatic cell lines compared to PM cells." (PMID 37047539, 2023). "By proteolysis, MMP3, another high-expression gene in PC samples, destroyed various molecules, such as ECM and adhesion molecules, and enabled the tumor to be more aggressive." (PMID 37727377, 2023). "More importantly, western blot and tumor immunohistochemical staining assays demonstrated decreased expression of MMP-2, MMP-3, and MMP-9 in the primary 4T1 tumor after D-NPBB94/C-NPBB94 treatment, which further confirmed its excellent therapeutic activity." (PMID 35440570, 2022).